ELFN1 (extracellular leucine rich repeat and fibronectin type III domain containing 1)
Description:
Postsynaptic protein that regulates circuit dynamics in the central nervous system by modulating the temporal dynamics of interneuron recruitment. Specifically present in excitatory synapses onto oriens-lacunosum molecular (OLM) interneurons and acts as a regulator of presynaptic release probability to direct the formation of highly facilitating pyramidal-OLM synapses (By similarity). Inhibits phosphatase activity of protein phosphatase 1 (PP1) complexes.
Synonyms: PPP1R28; DONDS
Tractability: Antibody: UniProt predicts a signal peptide or a membrane-spanning region; its Gene Ontology location is reachable by antibodies, with medium confidence. PROTAC: its protein half-life has been measured.
Gene: Protein-coding gene on chromosome 7 (1,665,745 to 1,747,946, forward strand). Ensembl gene ENSG00000225968.
Subcellular location: Membrane; Cell projection, dendrite; Cell projection, axon
Subcellular location (Human Protein Atlas): Cell Junctions; Nucleoplasm
Gene Ontology:
Molecular function: signaling receptor activity
Biological process: chemical synaptic transmission; synapse organization; establishment of protein localization; synaptic membrane adhesion
Cellular component: membrane; dendrite; excitatory synapse; plasma membrane; axon; postsynaptic density membrane
Genetic constraint (gnomAD): Loss-of-function variants: 6 observed, 5.43 expected, observed/expected ratio (o/e) 1.11, 90% interval 0.59 to 1.84. That is too few expected variants to judge how well the gene tolerates losing a copy. Missense variants: 1,169 observed, 1,083.1 expected, observed/expected ratio (o/e) 1.08, 90% interval 1.03 to 1.13. Synonymous variants: 657 observed, 522.25 expected, observed/expected ratio (o/e) 1.26, 90% interval 1.18 to 1.34.
Homologues: Orthologues: chimpanzee ELFN1 (99% identical), macaque ELFN1 (99% identical), guinea pig ELFN1 (91% identical), dog ELFN1 (90% identical), mouse Elfn1 (88% identical), rat Elfn1 (88% identical), pig ELFN1 (87% identical), tropical clawed frog elfn1 (66% identical), zebrafish elfn1b (59% identical), Drosophila melanogaster kek3 (14% identical), Caenorhabditis elegans sma-10 (11% identical), Drosophila melanogaster Con (11% identical), and 1 more. Paralogues in human: ELFN2 (47% identical), LRIG1 (15% identical), LRIG3 (14% identical), LRIG2 (13% identical), TRIL (11% identical), LGR6 (11% identical), LGI2 (11% identical), LGR4 (10% identical), LGR5 (10% identical), LGI1 (10% identical), LGI4 (10% identical), LRRC24 (10% identical), and 10 more.
Diseases named in the same sentence as ELFN1 in open-access papers:
ELFN1 is named in the same sentence as 41 diseases in open-access papers, as found by Europe PMC text mining. Sharing a sentence is not in itself a finding about the gene and the disease. The quoted sentences say what the papers report.
epilepsy (12 papers, 2013 to 2025). A brain disorder characterized by episodes of abnormally increased neuronal discharge resulting in transient episodes of sensory or motor neurological dysfunction, or psychic dysfunction. "Early studies on ADHD pointed to GRM7, and later, in ADHD and epilepsy, the interaction of mGlu7-Elfn1 has been implicated (Elfn1 is clustered in the carboxy-terminal region required for mGluR7 recruitment)." (PMID 40149928, 2025). "In recent years, ELFN1 has been increasingly implicated in human neurological disease etiology, including epilepsy, autism, post-traumatic stress disorder, attention-deficit/hyperactivity disorder, intellectual disability, and schizophrenia." (PMID 39675706, 2024). "In the case of ELFN1 four heterozygous variants were reported in a cohort of Japanese patients with neurological disorders, such as epilepsy or autism spectrum disorder." (PMID 34946966, 2021). "Although Elfn1 KO mice show hyperactivity and sensory-triggered epileptic seizures, damaging missense mutations of ELFN1 were found in clinical epilepsy and attention deficit hyperactivity disorder (ADHD) studies, suggesting evolutionary conservation across species." (PMID 40149928, 2025). "Notably, multiple missense ELFN1 mutations within the intracellular tail have been identified in a population of patients with epilepsy, attention-deficit/hyperactivity disorder, and/or autism spectrum disorders." (PMID 39675706, 2024). "ELFN1, a protein of the same family, has been reported to be associated with neuropsychiatric disorders (attention deficit hyperactivity disorder, post-traumatic stress disorder, and epilepsy)." (PMID 35396452, 2022). "Given the phenotypes we observe in mice, it seems plausible that severe mutations in the human ELFN1 gene (located at 7p22.3) could be involved in the etiology of rare cases of epilepsy, possibly involving symptoms of ADHD." (PMID 24312227, 2013). "Alterations to the molecular mechanisms of cell-type-biased and synapse-type-specific development may underlie aspects of neurodevelopmental disorders like autism and schizophrenia, as shown by the associations between mutations in Elfn1 and ASDs, epilepsy, and ADHD." (PMID 34630048, 2021). "We first assessed baseline neural activity and initial stimulus responses in Elfn1 WT and KO animals, as Elfn1 KO mice have some tendency toward epilepsy after 3 months of age, although with normal neuroanatomical development." (PMID 37709538, 2023). "In terms of clinical relevance, the current clinical results suggest the ELFN1 is genetically associated with ADHD, PTSD, and epilepsy." (PMID 33790745, 2021). "Heterozygous missense variants, p.Ala481Val, p.Arg650Cys, p.Asp678Asn, p.Arg691Trp, in ELFN1 have been identified in a Japanese cohort diagnosed with epilepsy, autism spectrum disorder (ASD), and attention deficit hyperactivity disorder." (PMID 34452636, 2021). "These analyses reveal a requirement for Elfn1 in brain function and are suggestive of possible relevance to the etiology and pathophysiology of epilepsy and attention-deficit hyperactivity disorder." (PMID 24312227, 2013). "In addition to ADHD/epilepsy, a recent study highlighted the involvement of ELFN1 in post-traumatic stress disorder (PTSD) pathophysiology." (PMID 33790745, 2021). "Of note, ELFN1 mutations clustered in the region required for mGlu7 recruitment have been found in patients with epilepsy and ADHD, and ELFN1 knockout (Elfn1-/-) animals exhibit a similar seizure phenotype to Grm7-/- animals." (PMID 30405350, 2018). "Importantly, both preclinical and clinical studies have provided support for the involvement of the Elfn1–mGluR7 interaction in attention-deficit hyperactivity disorder (ADHD), post-traumatic stress disorder (PTSD), and epilepsy." (PMID 33790745, 2021). "Epilepsy and ADHD may also involve mGluR7 interaction with Elfn1." (PMID 40149928, 2025).
attention deficit-hyperactivity disorder (9 papers, 2013 to 2025). A disorder characterized by a marked pattern of inattention and/or hyperactivity-impulsivity that is inconsistent with developmental level and clearly interferes with functioning in at least two settings (e.g. at home and at school). "Interestingly,individuals with mutations in ELFN1 or GRM7 genes present with attention-deficit hyperactivity disorder andepilepsy, and knockout mice of each of these proteins develop seizureswith very similar time courses." (PMID 40689847, 2025).
Headache (2 papers, 2022 to 2023). Cephalgia, or pain sensed in various parts of the head, not confined to the area of distribution of any nerve. "Moreover, neuronal hyperexcitability is also associated with neurological disorders, including migraines and headache, suggesting ELFN1 to be an exciting candidate gene for migraine susceptibility." (PMID 36808568, 2023). "A cross-trait genetic study very recently found ELFN1 implicated in migraine, headache, and T2D." (PMID 36808568, 2023). "The most significant locus for headache and T2D was near ELFN1 (lead SNP: rs73050128, Pmeta ≤ 1.50 × 10−11)." (PMID 36292730, 2022).
Anxiety (1 paper, 2013). Intense feelings of nervousness, tension, or panic often arise in response to interpersonal stresses. "Though habenular function has been implicated in regulating anxiety levels, this kind of phenotype could also be related to Elfn1 functions in any number of other regions, most obviously including the septum, extended amygdala and hippocampus." (PMID 24312227, 2013). "Elfn1 mutants also display reduced thigmotaxis, which is usually taken as a measure of anxiety levels and which is sensitive to dopaminergic signaling." (PMID 24312227, 2013).
Astigmatism (1 paper, 2021). A type of refraction error associated with abnormal curvatures on the anterior and/or posterior surface of the cornea. "ELFN1 and CCDC112: Using trio analysis we identified two de novo missense variants in the ELFN1 and CCDC112 genes in patient T62 with SM (−3.6), delayed myelination, asymmetric cerebral hemispheres, epileptic encephalopathy, hypotonia, sensorineural hearing loss, myopia and astigmatism." (PMID 34946966, 2021).
bone cancer (1 paper, 2025). A primary or metastatic malignant neoplasm affecting the bone or articular cartilage. "At both the RNA and protein levels, ELFN1 expression was detected in various tumor cell lines, with relatively high levels observed in sarcoma, rhabdoid (RB), gastric cancer, lymphoma, and bone cancer cell lines." (PMID 41357574, 2025).
colorectal cancer (1 paper, 2025). A primary or metastatic malignant neoplasm that affects the colon or rectum. "To further confirm the relationship between ELFN1 and colorectal cancer, we examined the expression status of ELFN1 in CRC cells." (PMID 41357574, 2025). "In agreement with a recent study, our in vitro experiments confirmed that ELFN1 promotes the proliferation, motility, and migration of colorectal cancer (CRC) cells." (PMID 41357574, 2025). "Finally, we assessed the effect of ELFN1 knockdown on colorectal cancer (CRC) cells using in vitro experiments." (PMID 41357574, 2025). "In colorectal cancer (CRC), ELFN1 has been identified as a potential neutrophil extracellular trap (NET)-associated differentially expressed gene (DEG) in prognostic models and exhibits positive correlation with the NETs signaling pathway." (PMID 41357574, 2025).
glioma (1 paper, 2025). A benign or malignant brain and spinal cord tumor that arises from glial cells (astrocytes, oligodendrocytes, ependymal cells). "In the UVM GSE139829 dataset and the Glioma GSE139448 dataset, ELFN1 was mainly expressed in malignant cells, with low expression in endothelial cells and fibroblasts." (PMID 41357574, 2025).
lymph node metastasis (1 paper, 2025). "Further analysis revealed that ELFN1 upregulation was closely associated with distant metastasis and lymph node metastasis in COADREAD." (PMID 41357574, 2025).
melanoma (1 paper, 2025). A malignant, usually aggressive tumor composed of atypical, neoplastic melanocytes. "Previous studies have demonstrated that ELFN1 plays a role in immune regulation and various biological processes in malignant tumors, including melanoma, colorectal, breast, and ovarian cancers." (PMID 41357574, 2025).
metastatic melanoma (1 paper, 2025). A melanoma that has spread from its primary site to another anatomic site. "Elevated ELFN1 expression is strongly associated with poor progression-free survival (PFS), overall survival (OS), and resistance to tumor-infiltrating lymphocyte (TIL) therapy in metastatic melanoma patients." (PMID 41357574, 2025).
microcephaly (1 paper, 2021). A congenital or acquired developmental disorder in which the circumference of the head is smaller than normal for the person's age and sex. "The functional data available for ELFN1 suggests its role in synaptic transmission by trans regulation of mGLUR7, whose mutations are already known to cause ASD, ID, microcephaly, hypotonia and seizures." (PMID 34452636, 2021).
ovarian carcinoma (1 paper, 2025). A malignant neoplasm originating from the surface ovarian epithelium. "In silico analysis of pan-cancer single-cell RNA sequencing datasets has revealed that ELFN1 is predominantly expressed in cancer-associated fibroblasts (CAFs) and endothelial cells across multiple cancer types, such as breast, lung, colorectal, and ovarian cancers." (PMID 41357574, 2025). "Furthermore, ELFN1 expression has been documented in other cancers, such as breast and ovarian cancers." (PMID 41357574, 2025).
neurological disorders (5 papers, 2021 to 2024). "Extracellular leucine rich repeat and fibronectin type III domain containing 1 (ELFN1) is a postsynaptic adhesion molecule in the brain that has been increasingly implicated in human neurological disease." (PMID 39675706, 2024). "Considering the earlier reports of ELFN1 involvement in neurological disorders in heterozygous state, we can conclude that homozygous variant detected in MRID175 is a likely cause of moderate ID." (PMID 34452636, 2021).
cancer (3 papers, 2021 to 2025). A tumor composed of atypical neoplastic, often pleomorphic cells that invade other tissues. "This study demonstrates that ELFN1 is aberrantly expressed in various cancers and is significantly associated with patient prognosis." (PMID 41357574, 2025). "Comparisons between normal and tumor tissues showed that ELFN1 expression was dysregulated in most tumor types and was associated with various clinical factors, underscoring its prognostic value in cancers such as CESC, COAD, KIRC, LIHC, LUAD, SKCM, and UVM." (PMID 41357574, 2025). "Our study revealed significant dysregulation of ELFN1 across various cancer types, with notable diagnostic and prognostic utility in most cancers analyzed." (PMID 41357574, 2025). "ELFN1 demonstrated high diagnostic accuracy in 5 cancers, moderate accuracy in 13 cancers, and low accuracy in 10 cancers." (PMID 41357574, 2025). "Alterations in the ELFN1 gene, including mutations, amplifications, and deletions, were identified across multiple cancer types." (PMID 41357574, 2025). "Dysregulated ELFN1 expression in certain cancers was associated with abnormal copy number variations and methylation patterns." (PMID 41357574, 2025). "ELFN1 showed significant associations with these markers, suggesting its role in genomic instability across cancers." (PMID 41357574, 2025). "We also performed pan-cancer analysis of the association between ELFN1 and immunoregulatory genes as well as immune checkpoint genes." (PMID 41357574, 2025). "Furthermore, ELFN1 was linked to poor prognosis in several cancers, suggesting its potential as a prognostic biomarker." (PMID 41357574, 2025). "ELFN1 was found to be upregulated in most cancers and exhibited high diagnostic value." (PMID 41357574, 2025). "ELFN1 expression was significantly associated with cancer stemness in multiple cancers." (PMID 41357574, 2025). "Our systematic analysis highlights the characterization of ELFN1 in cancer tissues and identifies its potential as an important prognostic biomarker and immunotherapeutic target for specific cancer types." (PMID 41357574, 2025). "In summary, these analyses indicate that ELFN1 plays an important role in DNA methylation and mRNA modifications across various cancer types." (PMID 41357574, 2025). "This study aimed to address this gap by conducting a multi-omics pan-cancer investigation of ELFN1 using a comprehensive array of datasets and tools to examine its relationship with clinical features and multi-omics heterogeneity." (PMID 41357574, 2025). "To further explore the potential of ELFN1 as a target for cancer immunotherapy, we analyzed the OS of patients with high or low ELFN1 expression who received anti-PD1, anti-PDL1, or anti-CTLA4 therapy." (PMID 41357574, 2025). "Extracellular leucine rich repeat and fibronectin type III domain containing 1 (ELFN1), a transmembrane protein implicated in tumorigenesis and therapy resistance, remains mechanistically undefined as a pan-cancer target." (PMID 41357574, 2025). "In this study, amplifications, mutations, and deep deletions were identified as the most frequent alterations in the ELFN1 gene across several cancer types." (PMID 41357574, 2025). "Through an integrated analysis of differential expression and prognostic data, COAD and SKCM emerged as the most pertinent cancer types, with ELFN1 showing the highest hazard ratio in COAD." (PMID 41357574, 2025). "Building on these findings, this study systematically analyzed the expression, prognostic significance, and functional roles of ELFN1 across multiple cancer types." (PMID 41357574, 2025). "Mechanistically, ELFN1 expression was associated with DNA methylation, DNA repair, genomic instability, and tumor microenvironment (TME) scores in multiple cancer types." (PMID 41357574, 2025). "To explore genomic alterations of ELFN1, we performed pan-cancer analyses of copy number variation (CNV) and single nucleotide variation (SNV) using the TCGA dataset and GSCA portal." (PMID 41357574, 2025).